SETDB1 (SET domain bifurcated histone lysine methyltransferase 1)
Diseases named in the same sentence as SETDB1 in open-access papers (continued):
Sharing a sentence is not in itself a finding about the gene and the disease.
tumor (continued). "Therefore, we speculated that decreasing SETDB1 expression in tumor cells might enhance immunotherapeutic responses." (PMID 35656340, 2022). "A deeper understanding of the molecular mechanisms of SETDB1 that regulate ERVs and immune genes in both tumour and normal cells and the availability of more selective and effective SETDB1 inhibitors may lead to SETDB1 targeting as a promising antitumour epigenetic therapy." (PMID 36582533, 2022). "As already mentioned, SETDB1 is not positively associated with tumourigenesis and progression of all malignancies, and it may act as a tumour suppressor in certain tumour types or at certain stages." (PMID 36582533, 2022). "Tumorigenesis is a great example of this enzyme’s functional variability since SETDB1 may acquire both a tumor-suppressive function in some tissues, as well as an oncogenic function in others, and thus can repress either tumor-suppressing or tumor-promoting genes, respectively." (PMID 34440561, 2021). "Furthermore, SETDB1 is highly upregulated in various tumor cells." (PMID 32486217, 2020). "Using data from the National Cancer Institute Clinical Proteomic Tumor Analysis Consortium (CPTAC) we further demonstrated that ZNF638, TASOR, MPHOSPH8, SETDB1 proteins were significantly enriched in GBM versus normal brain tissue." (PMID 40091830, 2025). "In a mouse model, SETDB1 knockout boosted PD-L1 levels and CD8+ T cell infiltration, increasing tumor sensitivity to anti-PD-L1 immune checkpoint therapy." (PMID 39949780, 2025). "Firstly, existing studies have shown that SETDB1 is the most significantly upregulated epigenetic regulator in human HCC, and its overexpression affects HCC progression, tumor invasiveness and poor prognosis." (PMID 39583200, 2024). "In this review, we discuss in detail the role and molecular mechanisms of SETDB1 overexpression in HCC, particularly its role in regulating tumor immune responses." (PMID 39583200, 2024). "SETDB1 overexpression is significantly correlated with HCC progression, tumor aggressiveness (such as tumor microsatellite formation and metastasis), and poor prognosis of HCC patients." (PMID 39583200, 2024). "To further verify the effect of SETDB1 knockout on HCC tumorigenicity in vivo, we constructed a subcutaneous xenograft tumor model." (PMID 39768193, 2024). "Our findings revealed that both SETDB1 and MCT1 were significantly overexpressed in the majority of paired CRC tumor tissues when compared to adjacent normal tissues." (PMID 37541664, 2023). "Analysis of CHD1L correlated proteins in the tumor tissue revealed that POLR3C, PRKAB2, SETDB1, GPATCH4, and MSTO1 were the top five ones." (PMID 37033447, 2023). "The mRNA expression levels of SETDB1 in HNSC-HPV+ tumor and SKCM-Metastasis tissues were higher than those in HNSC-HPV− tumor and SKCM primary tumor tissues." (PMID 35656340, 2022). "Elevated SETDB1 has been observed in CRC, and its upregulation is able to induce proliferation of CRC cells and tumor growth in CRC." (PMID 35497876, 2022). "Analysis of RACGAP1 correlated proteins in the tumor tissue revealed that POLR3C, PRKAB2, SETDB1, GPATCH4, and MSTO1 were the top five." (PMID 36430577, 2022). "As a tumour suppressor, SETDB1 cooperates with SMAD2/3 complex to form the SETDB1-SMAD 2/3 inhibitory complex in metastatic lung cancer cells." (PMID 34299035, 2021). "In contrast, in the invasive front of tumor cells undergoing TGF-β-induced EMT, SETDB1 expression is repressed by TGF-β to de-repress the Smad3-SETDB1-mediated repression of the Snail promoter." (PMID 32114978, 2020). "However, compared to relative isoform expression in normal and immortalized cell lines, full-length SETDB1, similar to PR (PRDI-BF1 and RIZ1 homology) domain-containing HMTs, may be tumor-suppressive, whereas the splice variant was overexpressed in the immortalized cell lines." (PMID 31405032, 2019).
tumor (continued). "The predicted effects of SETDB1 expression on tumor biology do not fully account for the poorer survival outcomes observed in patients with high SETDB1 expression (SH group) within the TCGA-LIHC cohort." (PMID 41493679, 2026). "Together, these results support a model in which SETDB1 drives dedifferentiation and stemness in HCC through coordinated transcriptional and signaling networks, fostering intratumoral plasticity and aggressive tumor behavior." (PMID 41493679, 2026). "SETDB1 promotes tumour progression through multiple mechanisms, including gene silencing, epithelial-mesenchymal transition (EMT), drug resistance, methylation and activation of AKT, immune cell function and tumour immunotherapy." (PMID 38317200, 2024). "Lysine Demethylase 5B (KDM5B) recruits SETDB1 to inhibit endogenous retroelements in a demethylase-independent manner, thereby inhibiting the cGAS-STING pathway and type-I interferon response, which contributes to tumor growth and immune memory inhibition." (PMID 38057834, 2023). "These challenges highlight the need to elucidate the differences and specific mechanisms of SETDB1 interaction with relevant target proteins, ERVs and immune genes across different tumour types and noncancerous cells." (PMID 36582533, 2022). "They identified SETDB1 (or SETDB1 recruited by KDM5B) as a chromatin regulator that depresses tumour-intrinsic immunogenicity and mediates immune tolerance in both mice and human tumours, and SETDB1 depletion potently boosted the efficacy of ICB in mouse models." (PMID 36582533, 2022). "Amplified or overexpressed SETDB1 levels often induce excessive H3K9 trimethylation at promoter regions, which changes the local structural dynamics of chromatin and finally leads to abnormally silenced tumour-suppressive genes and tumourigenesis." (PMID 34299035, 2021). "SET domain bifurcated 1 (SETDB1) is upregulated in GBM and promotes AKT/mTOR-dependent CSF-1 induction and secretion, which leads to macrophage recruitment in the tumor, resulting in tumor growth." (PMID 34071306, 2021). "SETDB1 primarily represses gene expression with chromatin remodelling based on its methyltransferase activity at H3K9, through which it exerts various functions, including ERVs silencing, XCI and tumour-suppressive genes repression." (PMID 34299035, 2021). "SETDB1 transcriptionally represses TEs as an effector in the KAP1-built repressive complex; therefore, it stands to reason to give the first consideration to these TEs for their expression change in the SH tumor samples." (PMID 33343623, 2020). "It is therefore vital for tumour cells to tightly regulate IFN signalling to survive treatment, which is plausibly mediated through the attenuation of ISGs by SETDB1/2 following an initial burst of inflammation and dedifferentiation that promotes their activation." (PMID 30850015, 2019). "In vivo tumour growth was dramatically retarded by induction of SETDB1-inducible shRNA, without significant drop of body weight." (PMID 26471002, 2015). "In addition to the 8 representative PKMTs with tumor suppressor activity, PRDM16, MLL2, MLL4, SET domain bifurcated histone lysine methyltransferase 1 (SETDB1), SETD3, NSD1, NSD3, DOT1L, SUV39H1, and SUV39H2 have also been suggested to possess tumor suppressor activity." (PMID 38036730, 2023).
tumor (continued). "Encouraged by these data, we conducted a subcutaneously implanted tumor model by injecting these cells into BALB/c mice, which showed that SETDB1 could significantly promote tumor progression in MCT1 WT CT26 cells, but not in MCT1 K467R CT26 cells." (PMID 37541664, 2023). "SETDB1 could catalyze the methylation of histone H3K9, and excessive H3K9 trimethylation products promote the inhibition of tumor suppressor factors, leading to tumor occurrence." (PMID 37220590, 2023). "Moreover, SETDB1 has been shown to be involved in the formation of PML-NBs, which play a major role in apoptosis, the maintenance of embryonic stem cell pluripotency, DNA damage response and cellular stress as well as tumor growth inhibition." (PMID 34440561, 2021). "Although the tumor-suppressive role of AKT3-174aa prevents its druggable potential, we think that the low expression of AKT3-174aa may allow for AKT be easily exposed to p-PDK1 or SETDB1 in GBM, and this makes AKT more sensitive to activation cascades." (PMID 31470874, 2019). "However, we have not completely explored tumorigenesis mechanism of SETDB1, which is associated with the growth and metastasis of HCC tumor." (PMID 29739365, 2018). "We performed histopathology analysis of the tumours with or without SETDB1 knockdown." (PMID 26471002, 2015). "However, mithramycin, a clinically anti-tumor antibiotic, has been reported to nonspecifically suppress SETDB1 expression in a dose-dependent manner, which binds to GC-rich regions of genome thus interferes with the association of transcriptional activators at Setdb1 promoters." (PMID 34294683, 2021). "However, although the bulk tumor levels may have been reduced, this phenomenon alone does not warrant it to be sufficient evidence in categorizing mithramycin A as specific SETDB1 target or in suggesting it to abrogate CSC development." (PMID 31405032, 2019). "While these data indicate that phf7 is a critical target of SETDB1 silencing, our finding that the phenotype was not fully rescued suggests that ectopic expression of one or more of the other SETDB1 target genes we identified in this study also contribute to the tumor phenotype." (PMID 30297796, 2018). "It is also unknown whether ATRX, KDM5 and/or SETDB1 are involved in the suppression of R loops, rather than, or in addition to, NAS suppression in tumor cells or during the establishment of DTPs." (PMID 35602594, 2022).
infection (8 papers, 2011 to 2025). The state of being infected such as from the introduction of a foreign agent such as serum, vaccine, antigenic substance or organism. "SETDB1 expression can be knocked down through stable infection of dCas9-KRAB and gRNAs targeting the SETDB1 gene." (PMID 37020498, 2023). "In contrast, given the essential role of TRIM28/SETDB1 in innate and adaptive immune responses, its preserved expression may contribute to maintaining effective immune protection against infection." (PMID 36826024, 2023). "Furthermore, the decrease in cellular apoptosis and the corresponding modulation of gene expression triggered by SETDB1 inhibition was reversed by AAV9-ASK1 infection." (PMID 37915765, 2023). "Furthermore, after 36 h of infection with two shRNA lentivirus targeting SETDB1 respectively, the cell morphology was changed, which is similar to that after deletion of TRIM28, and deletion of SETDB1 also decreased the level of C-circle in U2OS cells." (PMID 34330324, 2021). "Importantly, SETDB1 and HP1α recruitment as well as H3K9 trimethylation were lost when KAP1 was depleted by RNA interference prior to HSC infection, supporting a model whereby the corepressor recruits these heterochromatin-inducing factors." (PMID 25846574, 2015). "Given the negative impact of HERVs and the positive effects of TRIM28/SETDB1 on innate and adaptive immune responses, the downregulation of the former and the normal expression of the latter may contribute to preserving immune functions against infection." (PMID 36826024, 2023).
hematologic malignancies (2 papers, 2018 to 2026). "The histone KMT SETDB1, a key stemness factor both in embryonic and adult stem cells, has emerged as a predominant oncogene in a wide range of solid cancers and hematological malignancies promoting chemoresistance." (PMID 41493679, 2026). "The histone methyltransferase SETDB1, a key stemness factor in both embryonic and adult stem cells, catalyzes H3K9 trimethylation (H3K9me3) and acts as a major oncogenic driver in a wide range of solid and hematological malignancies." (PMID 41493679, 2026).
neurologic disorders (2 papers, 2018 to 2023). "The link between SETDB1 and neurological disorders extends beyond what is described here for IL1RAPL1, as neuronal ablation of SETDB1/Setdb1 results in heterochromatin loss and disrupted expression at the protocadherin cluster." (PMID 30103804, 2018). "TRIM28 and SETDB1 are highly expressed in the CNS, participating in the differentiation of cell lineages within the brain, and their alterations or of their substrates have been found in several neurologic disorders." (PMID 36992419, 2023).
bacterial infection (1 paper, 2016). "For instance, Setdb2, the family member most closely related to Setdb1, mediates virus-induced susceptibility to secondary bacterial infection by regulating CXCL1 transcription." (PMID 27349785, 2016).
brain disorder (1 paper, 2020). A disease affecting the brain or part of the brain.
gastrointestinal system disorders (1 paper, 2021). "Aberrant SETDB1 activity has been ultimately linked to disease onset, including nervous, cardiovascular and gastrointestinal system disorders, as well as numerous inherited genetic syndromes." (PMID 34440561, 2021).
hematological cancer (1 paper, 2021). "We identified recurrent highly pathogenic variants affecting important drivers of hematological cancer (ATM), epigenetic regulators (ISX and SETDB1), and mediators of DNA replication (POLQ)." (PMID 33809641, 2021).
psychiatric disorder (1 paper, 2020). A disorder characterized by behavioral and/or psychological abnormalities, often accompanied by physical symptoms. "Considering the reversible property of SETDB1 as an epigenetic enzyme, it holds the potential for the treatment of psychiatric disorders." (PMID 32321908, 2020).
SETDB1 also shares sentences with these, for which no sentence is quoted: colon adenocarcinoma (3 papers); nasopharyngeal carcinoma (3); breast invasive carcinoma (2); celiac disease (2); Duchenne muscular dystrophy (2); esophageal carcinoma (2); head and neck cancer (2); lung squamous cell carcinoma (2); rectum adenocarcinoma (2); adenocarcinoma (1); adenoma (1); adrenocortical carcinoma (1); Aicardi-Goutieres syndrome (1); Alpha-thalassemia (1); ameloblastoma (1); autism (1); cardiovascular diseases (1); cholangiocarcinoma (1); Cirrhosis (1); colitis (1); Crohn disease (1); Diarrhea (1); diffuse astrocytoma (1); diffuse large B-cell lymphoma (1); frontotemporal dementia (1); gastrointestinal disease (1); genetic disorders (1); head and neck squamous cell carcinoma (1); high-grade gliomas (1); hypogonadism (1).
A further 24 diseases each share a sentence with SETDB1 in 1 paper.